LARP1 (La ribonucleoprotein 1, translational regulator)
Diseases named in the same sentence as LARP1 in open-access papers (continued):
Sharing a sentence is not in itself a finding about the gene and the disease.
lung adenocarcinoma (1 paper, 2022). A carcinoma that arises from the lung and is characterized by the presence of malignant glandular epithelial cells. "In lung adenocarcinoma, we found that high expression levels of LARP1 are correlated with poor survival and nuclear cap-binding protein 1 (NCBP1)." (PMID 35982949, 2022).
lymph node metastasis (1 paper, 2016). "Using immunohistochemical analysis, the upregulation of LARP1 in CRC tissues was found to be significantly associated with clinical pathological characteristics, such as tumor size, AJCC stage, depth of invasion, lymph node metastasis, distant metastasis, and tissue differentiation." (PMID 27614686, 2016).
microcephaly (1 paper, 2025). A congenital or acquired developmental disorder in which the circumference of the head is smaller than normal for the person's age and sex. "This similarity to microcephaly we observe in Larp1 cKO mice suggests that Larp1 inactivation and subsequent depletion of ribosomal protein mRNAs might slow brain growth through similar mechanisms." (PMID 41278816, 2025).
myelodysplastic syndrome (1 paper, 2021). A clonal hematopoietic disorder characterized by dysplasia and ineffective hematopoiesis in one or more of the hematopoietic cell lines. "Interestingly, LARP1 was also suggested to play a role in 5q− myelodysplastic syndrome (MDS), which is a type of anaemia characterized by reduced TOP mRNA levels." (PMID 32233986, 2021).
ovarian tumour (1 paper, 2016). "As LARP1 is highly expressed in ovarian tumours, we hypothesized that patients with underlying malignancy may have higher levels of circulating protein." (PMID 26717985, 2016). "To determine whether LARP1-mediated regulation of cancer cell survival was important for ovarian tumour development, we induced stable knockdown of LARP1 (shLARP1) in SKOV3 cells (inset) and implanted them into SCID-beige mice." (PMID 26717985, 2016). "Supporting a clinically meaningful role for LARP1 in the post-transcriptional regulation of BCL2 and possibly also BIK expression in ovarian malignancies, expression of LARP1 positively correlates with BCL2, but is negatively correlated with BIK expression in a study of over 400 ovarian tumours." (PMID 26717985, 2016).
Sjögren's syndrome (1 paper, 2020). "Although La, the founding member of the Larp family, was first discovered as an auto-antigen in individuals with lupus erythromatosis and Sjögren's syndrome, and genetic variation of LARP1, LARP4A, LARP4B and LARP7 are observed in cancers, the role of LARP6 in human disease is as yet unclear." (PMID 32054660, 2020).
squamous cervical cancer (1 paper, 2016). "We have shown previously that expression of LARP1 is elevated in squamous cervical cancer, that LARP1 promotes cell motility and invasion, and is complexed with an mRNA interactome enriched for oncogenic transcripts." (PMID 26717985, 2016).
type 2 diabetes (1 paper, 2021). "Single-cell transcriptome profiling of human β-cells in healthy subjects and type 2 diabetes (T2D) further corroborates that LARP1 is the most abundant LARP in β-cells with similar pattern seen in T2D." (PMID 33483593, 2021). "Moreover, LARP1 is up-regulated in β-cells in patients diagnosed with type 2 diabetes." (PMID 33483593, 2021).
cancer (47 papers, 2013 to 2025). A tumor composed of atypical neoplastic, often pleomorphic cells that invade other tissues. "LARP1 also interacts with a large number of mRNAs in mTOR-independent pathways and has been implicated in cancer." (PMID 39016322, 2024). "This was also in keeping with the clinicopathological data from our team and others showing higher levels of LARP1 protein within tumours was associated with more aggressive cancer growth and worse patient outcome." (PMID 32233986, 2021). "We saw a similar reduction in proliferation in human immortalized non-cancer cell lines after loss of LARP1." (PMID 32233986, 2021). "In our lab, using various ovarian and other cancer cell lines, we have been unable to demonstrate an association between LARP1 and RAPTOR under any conditions tested." (PMID 32233986, 2021). "LARP1 encodes an RNA-binding protein that is necessary for cancer cell survival and ribosome biogenesis." (PMID 33614632, 2020). "As deletion of Arf is a common occurrence in cancer, exploring the co-occurrence of Arf-loss and increased LARP1 or eIF4G1 expression seems warranted." (PMID 33335292, 2020). "Ingenuity gene ontology analysis revealed transcripts with altered levels on LARP1 knockdown were significantly enriched for functions linked to cancer." (PMID 26717985, 2016). "By visualizing the organization of the key amino acids predicted to mediate mRNA binding by LARP1, we provide potential therapeutic avenues for controlling the pathogenic RNA binding activity of LARP1 in cancer." (PMID 26206669, 2015). "Additionally, single-cell sequencing in the study revealed that high expression of LARP1 is closely associated with cancer-associated fibroblasts (CAFs), which are known to play a key role in tumor immune evasion and metastasis." (PMID 40018039, 2025). "Changes in LARP1 levels are associated with cancer progression." (PMID 38283117, 2024). "Another gene, the La-related protein 1 (LARP1), has been shown to interact with 3000 mRNAs linked to cancer pathways, including post-transcriptionally controlled mTOR which was frequently dysregulated in cancer, promoting cell motility, invasion, and anchorage-independent growth." (PMID 35982949, 2022). "Translation of 5′-TOP motif-containing mRNAs is activated during cancer cell invasion, migration and metastasis, with RNA-binding proteins such as LARP1, CNBP, AUF1 and TIAR1 involved in this process." (PMID 40855114, 2025). "Intriguingly, LARP1, a keystone in the mTOR pathway's influence on cancer metastasis, caught our attention as a potential interactor with TBG." (PMID 39786317, 2025). "The mRNA stability of a proapoptotic gene BCL-2 interacting killer (BIK) is suppressed by La-related protein 1 (LARP1), a protein highly expressed in cancer cells." (PMID 41280104, 2025). "The correlation between LARP1 and multiple human cancers is becoming more evident with each new research finding." (PMID 39786317, 2025). "While the involvement of LARP1 in the metastatic process of various cancers has been documented, there is a noticeable gap in the literature regarding its potential influence on ATC metastasis." (PMID 39786317, 2025). "LARP1 is an oncogene RNA binding protein essential for ribosome biogenesis and cancer cell survival." (PMID 39159158, 2024). "Some studies have reported that metastasis, a crucial event in cancer progression, is affected by LARP1 expression." (PMID 38283117, 2024). "As an oncogenic RNA-binding protein, LARP1 alters gene function and drives cancer development through abnormal changes in post-transcriptional regulation." (PMID 38283117, 2024). "In hepatoblastoma, O-GlcNAcylation of La-related protein (LARP1), which is an RNA-binding protein and is involved in various cancers, protects the protein from proteasome-dependent degradation." (PMID 37838167, 2023). "Increased LARP1 level enhances the expression of β-catenin increasing cancer cell proliferation and tumor progression." (PMID 37838167, 2023).
cancer (continued). "EIF3D was identified to enhance the sensitivity of cancer cells to some chemotherapeutics, such as hydroxyurea, chelerythrine, and vorinostat, while LARP1 weakened the sensitivity of denileukin diftitox ontak." (PMID 35602299, 2022). "Further studies should establish the dynamic of LARP1 upstream regulator in relation to position of cancer cells within the tumor." (PMID 35512017, 2022). "La-related protein 1 (LARP1), conserved RNA-binding protein, exerts its cancerogenic functions via mediating multiple malignant behavior in cancer cells." (PMID 35365169, 2022). "Peg10 is a known oncogene and has been shown to interact with Nanog and Oct4 in human cancer cells, and Larp1 is thought to regulate translation downstream of the mTor pathway." (PMID 33863351, 2021). "Although some cancers co-express high levels of LARP1 and mTOR, for the majority of cancers they are uncoupled." (PMID 32233986, 2021). "Since this initial observation shared with me at a conference in 2012 and later published, others have established LARP1 as a pivotal node in mTORC1 signalling, solidifying its role in biologically critical pathways that are deregulated in cancer." (PMID 32233986, 2021). "By contrast, in a range of cancer cells, depletion of LARP1 induced apoptosis, particularly in those exposed to cell stress." (PMID 32233986, 2021). "LARP1 is an oncogenic RNA-binding protein required for ribosome biogenesis and cancer cell survival." (PMID 32286153, 2021). "As nutrient-dependent phospho-regulation by mTORC1 is perhaps the default role for LARP1, an understanding of its switch to stress-regulated survival signalling is the key to unlocking its function in cancer and other diseases." (PMID 32233986, 2021). "We have consistently observed that cancer cells with high levels of LARP1 have strong dependence on it for survival." (PMID 32233986, 2021). "To explore this, we systematically conducted a series of in silico, transcriptomic, biochemical and cellular assays to elucidate the true expression profile of LARP1 in cancer and normal cells." (PMID 32286153, 2021). "When we correlated the expression levels of mTOR and LARP1 in a series of cancer cases, there was a weakly positive correlation between the two (r = 0.29) indicating LARP1 and mTOR often function independently of each other." (PMID 32233986, 2021). "Here, the cancer cell is exquisitely dependent on LARP1 for the translation of essential oncogenic proteins when cap-mediated translation is repressed." (PMID 32233986, 2021). "LARP1 is a conserved RNA-binding protein to control ribosome biogenesis, and participates in cancer cell survival, thus representing cancer therapeutic target." (PMID 33347535, 2021). "The combined expertise of the LARP1 community will allow us to reveal all of the wonderful intricacies of this protein and its role in healthy cells, in cancer, and in viral infection." (PMID 32233986, 2021). "Altogether, our data indicate that the mRNA for the long LARP1 isoform is the dominantly expressed form in wide range of cancer and normal cells and that the SI-LARP1 mRNA, if expressed, is present at low levels and in an immature form." (PMID 32286153, 2021). "The LARP1 protein is highly expressed in various malignant tumors and is a predictor of adverse prognosis in cancer." (PMID 32953888, 2020). "In connection with this, LARP1 as a substrate of CDK1 is upregulated in certain cancer types, which leads to an elevated survival rate probably via aberrant translation." (PMID 32605021, 2020). "For example, in cancer cells LARP1 has positive effects on total protein synthesis and binds to a range of targets including those that encode proto‐oncogenes in addition to TOP‐containing mRNAs." (PMID 29341429, 2018). "In cancer cell lines, LARP1 has been shown to bind an interactome of approximately 3000 mRNAs that is enriched for transcripts encoding cell survival and RNA biogenesis proteins." (PMID 28762650, 2018).
cancer (continued). "It is unclear what drives LARP1 expression in this context, although cancer cells are often exposed to aberrant growth factor signaling." (PMID 29341429, 2018). "Our data demonstrated mRNA PAT net lengthening activity for two other La module proteins, LARP4B and LARP1, the latter of which is a regulator of ribosome biogenesis and a pro-cancer protein." (PMID 28895529, 2017). "This study found that the elevated expression of LARP1 correlated positively with PCNA expression, suggesting that LARP1 mediated cancer cell proliferation." (PMID 27614686, 2016). "In a previous systematic screen of LARP1 expression in diverse malignancies, we found that the protein was highly expressed in several different cancer types, including EOC." (PMID 26717985, 2016). "Of the LARPs, La, LARP1 and LARP7 have also been implicated in cancer, albeit with rather distinct mechanisms." (PMID 27615744, 2016). "We show, using ovarian cell lines and xenografts, that LARP1 is required for cancer cell survival and chemotherapy resistance." (PMID 26717985, 2016). "Although representing opposing effects on RNA stability, the anticipated net consequence of increased LARP1 is to enhance cancer cell survival." (PMID 26717985, 2016). "In several cancers, the relationship between LARP1 expression and clinical outcome has been studied." (PMID 26501340, 2015). "Overall, we see that LARP1 is involved in modulating the tumorigenicity of cancer cells and its overexpression drives tumor progression in vivo." (PMID 25531318, 2015). "Although we show the net effect of LARP1 in these cancer cells is to stabilize and enrich protein expression, confirmed here at transcript level with mTOR, it is possible that LARP1 destabilizes some transcripts while stabilizing others." (PMID 25531318, 2015). "Further, its downstream location within the mTORC1 cascade and its direct control over proliferation via TOP regulation makes LARP1 a potential anti-cancer target." (PMID 26206669, 2015). "Upregulation of LARP1 occurs in several cancers, including that of the liver, cervix and breast, and is correlated with tumor progression and adverse clinical outcome." (PMID 26206669, 2015). "This implies that in cancer cells the LARP1 interactome is more extensive than has been described previously." (PMID 25531318, 2015). "In the malignant cells in which it has been characterised, the LARP1 interactome includes multiple cancer-sustaining targets especially those involved in cell survival." (PMID 26501340, 2015). "We therefore conclude that, through the post-transcriptional regulation of genes such as mTOR within cancer pathways, LARP1 contributes to cancer progression." (PMID 25531318, 2015). "The LARP1 protein expression was generally weak in adjacent non-cancer tissue samples and early stage HCC (TNM stages I and II), but strong in later stage HCC (TNM stages III) tissues." (PMID 24159927, 2013). "Quantitative analysis of the IHC staining indicated that LARP1 expression in clinical stage I–III primary tumors was statistically higher than that in adjacent non-cancer tissue samples (P < 0.05)." (PMID 24159927, 2013). "Moreover, LARP1 has been found to facilitate the onset and metastasis of various cancers via the mTOR pathway." (PMID 39786317, 2025). "TOP mRNAs account for less than 4% of mRNAs bound by LARP1 in cancer cells." (PMID 39016322, 2024). "Moreover, post‐translational modification (PTM) of LARP1, here referring to phosphorylation, has been reported to determine its contrary regulatory role in TOP mRNA translation, and LARP1 has been connected to various cancers." (PMID 37070251, 2023). "However, few studies have focused on LARP1 stabilizing or destabilizing other cancer‐related transcripts." (PMID 37070251, 2023). "Additionally, analysis of drug sensitivity indicated that EIF3D, EIF4A1, and LARP1 expressed by cancer cells greatly influenced the sensitivity of the cells to chemotherapy." (PMID 35602299, 2022).
cancer (continued). "LARP1 can also regulate mTOR signaling to contribute to cancer progression." (PMID 35785179, 2022). "In conclusion, hsa_circRNA_002144 could sponge miR-615-5p to promote CRC progression through the regulation of LARP1, providing a therapeutic target for cancer intervention." (PMID 33347535, 2021). "This indicates that LARP1 has a pro-survival role in certain cancer cells." (PMID 32233986, 2021). "Moreover, in several different types of cancer, conditions where cell survival and proliferation are enhanced, highly phosphorylated LARP1 has been reported." (PMID 33483593, 2021). "In LARP1-dependent cancer cells, LARP1 is phosphorylated by mTOR or by other pro-mitogenic kinases (such as CDK1 or AKT) and thus LARP1-mediated translational activation may be mTOR-dependent or independent." (PMID 32233986, 2021). "Interestingly, recent CRISPR-based essentiality screens have shown that cancer cell lines that are dependent on LARP1 are also likely to require LARP4A for proliferation." (PMID 32233986, 2021). "LARP1 functions as a molecular switch for mTORC1-mediated translation of an essential class of mRNAs and posttranscriptionally regulates mTOR and contributes to cancer progression by regulating cell division, apoptosis, and cell migration." (PMID 33614632, 2020). "These evolutionary insights may prove useful for ongoing investigations of the role of LARP1 in cancers, genetic disorders, and infection by viruses." (PMID 33054972, 2020). "LARP1 has previously been identified as a predictor of poor prognosis in hepatocellular and lung cancers, indicating it may be important in driving malignant progression across multiple tumour types." (PMID 26717985, 2016). "In contrast to La and LARP1, LARP7 is lost or mutated in a number of cancers." (PMID 27615744, 2016). "LARP1 promotes tumour formation in vivo and maintains cancer stem cell-like populations." (PMID 26717985, 2016). "In cancer cells, upregulation of LARP1 increases cell migration, invasion, EMT and tumourigenesis." (PMID 26501340, 2015). "Importantly, because the expression of LARP1 is upregulated in several cancers and the conserved C-terminal LARP1-region is predicted to be exclusive to LARP1, our crystal structure reveals a unique target for future drug design studies." (PMID 26206669, 2015). "Additionally, it remains to be determined if there is a concentration dependence on the LARP1:RNA stoichiometry in the cell, since in cancer cells, in particular, there is a significant increase in LARP1 expression." (PMID 26206669, 2015). "This dimerisation may be concentration-dependent, and thus more prevalent in cancer cells with higher levels of LARP1." (PMID 26501340, 2015). "Here, we show that LARP1 is complexed to 3000 mRNAs enriched for cancer pathways." (PMID 25531318, 2015). "Furthermore, since the role of mTOR-LARP1 axis in cancer cellular progression is universally agreed, we assumed that LARP1 might exert its function in ccRCC through this axis, which requires in-depth investigation in our future study." (PMID 33680937, 2020). "This further suggests that PAT-mediated mRNA stability by LARP1 may be uncoupled from translation repression including when LARP1 is over-expressed as occurs in certain cancers and associates with non-TOP mRNAs." (PMID 28895529, 2017). "An elevated protein expression of EIF4E, EIF4G3, LARP1, METTL1, NCBP1, NUDT4, and NUDT11 was discerned in the carcinoma samples, whereas the WDR4 expression was comparable between the tumor and adjacent non‐tumorous tissues." (PMID 40485623, 2025). "Some members of this superfamily, such as LARP1 and LARP6, control the expression of target transcripts and promote the progression of several cancer types." (PMID 31847302, 2019). "The correlation between LARP1 and PCNA in cancer cell proliferation was determined using the Spearman’s correlation coefficient test." (PMID 27614686, 2016).